MDH2 (malate dehydrogenase 2)
Diseases named in the same sentence as MDH2 in open-access papers (continued):
Sharing a sentence is not in itself a finding about the gene and the disease.
tumor (continued). "Of the top 20 differentially expressed proteins identified in tumour samples, four (MDH2, FASN, EPCAM, and HSD17B10) are targetable by FDA-approved drugs, whereas two (AMACR and GLYATL1) are potentially targetable and are of potential interest for future research." (PMID 38052461, 2024). "Our study elucidates that the interaction between MDH2 and FSP1 regulates susceptibility to ferroptosis in ccRCC, thereby providing novel insights into the potential role of common metabolic enzymes in regulating tumorigenesis and tumor progression." (PMID 39138167, 2024). "Moreover, considering MDH2’s role in tumor immunity, combining small-molecule MDH2 inhibitors with immune checkpoint inhibitors may enhance the efficacy of tumor immunotherapy." (PMID 41179294, 2025). "Furthermore, MDH2 deficiency sensitizes HCC cells to ferroptosis, which inhibits HCC tumor growth." (PMID 39519171, 2024). "So, it might improve the tumor reprogramming process by regulating the expression of MDH2." (PMID 28423718, 2017). "Targeting MDH2 has been shown to effectively inhibit GSC proliferation and self-renewal and suppress tumor growth in vivo." (PMID 40255400, 2025). "Given the fact that our results showed that MDH2 is overexpressed in HCC and promotes HCC tumor growth and ferroptosis evasion." (PMID 39519171, 2024). "In most tumor models, lnc-GAS5, mainly located in the cytoplasm, is demonstrated to translocate to mitochondria and suppress the TCA cycle by interacting with the MDH2 protein." (PMID 37770905, 2023). "Besides that, the Mdh1 and Mdh2 proteins that are related to mitochondrial catalytic activity and, together with the Pdhb protein, responsible for the conversion of pyruvate to Acetyl-CoA, showed high concentration in both groups supplemented with leucine, including the tumour-bearing group (L, WL)." (PMID 32668598, 2020). "In this study, we integrated data from The Cancer Genome Atlas (TCGA), Genotype-Tissue Expression (GTEx), Human Protein Atlas (HPA), Tumor Immune Estimation Resource (TIMER), transcriptomics, and metabolomics to identify MDH2 as a key metabolic enzyme in BRCA progression." (PMID 41179294, 2025). "However, LW6 is known to inhibit not only MDH2 but also HIF-1α (hypoxia-inducible factor 1α); LW6 is thought to suppress the growth of some tumor cells by inducing HIF-1α degradation, at least in part." (PMID 38339168, 2024). "To further investigate the expression of MDH2 in ccRCC, we assessed the expression of MDH2 in tumor tissues of the kidney and the adjacent non-tumor tissues of 85 patients diagnosed with ccRCC using immunohistochemical (IHC) staining analysis." (PMID 39138167, 2024). "Additionally, when we treated the MDH2 knockout group with the ferroptosis inducer SAS, the tumor volume and weight were still significantly increased compared with the NC group." (PMID 39138167, 2024). "MDH2 could regulate the mitochondrial NADH/NAD+ redox state to support ATP production, the expression of MDH2 possibly reflected metabolic reprogramming of mitochondria and correlate with tumor cell proliferation." (PMID 28423718, 2017). "Parallel to the succinate accumulation hypothesis, defects in three other TCA cycle enzymes have been linked to competitive inhibition of α-KG-dependent dioxygenases and tumor formation: isocitrate dehydrogenase (IDH), fumarate hydratase (FH), and malate dehydrogenase 2 (MDH2)." (PMID 26294907, 2015).
infection (13 papers, 2009 to 2025). The state of being infected such as from the introduction of a foreign agent such as serum, vaccine, antigenic substance or organism. "It is most likely that the infection hampered the tricarboxylic acid (TCA) cycle, because several genes (such as Sdhaf3, Sucla2, Idh3a and Mdh2) encoded the key enzymes in TCA cycle were significantly downregulated." (PMID 36618398, 2022). "We also found upregulation of key TCA cycle genes, including those encoding for succinate dehydrogenase (Sdhb) and malate dehydrogenase (Mdh1, Mdh2) during infection, which could contribute to reactive oxygen species (ROS) generation." (PMID 37923768, 2023). "We confirmed that the mRNA expression of Mdh2 and Idh2 was altered post infection (P< 0.01)." (PMID 36618398, 2022). "ISKNV mainly promoted the expression of MDH1, GOT1, MDH2 and GOT2 in the early stage of infection and further facilitated energy supply, ultimately promoting the proliferation of ISKNV." (PMID 39459874, 2024). "Above results indicated that SCRV infection mainly promoted the expression of GOT1 in the early stage, and promoted the expression of MDH2, GOT2, and ASNS in CPB cells in the late stage." (PMID 37065159, 2023). "Moreover, a decreased expression of enzyme subunits (MDH2 and SUCLA2) and an elevated expression of ACO1 and SUCLG2 in the cycle were observed post infection." (PMID 37256871, 2023).
metabolic disorder (5 papers, 2014 to 2024). "Inherited deficiency of MDH2 is an ultra-rare metabolic disease." (PMID 38425868, 2024). "This dual localization of Mdh2 contributes to our understanding of the glyoxylate cycle and provides a new perspective on compartmentalization of cellular metabolism, which is critical for the perception of metabolic disorders and aging." (PMID 33177075, 2020).
neurological disease (2 papers, 2017 to 2018). "Muscle involvement in addition to neurological disease is also seen in mutations of the malate dehydrogenase gene, MDH2." (PMID 30478029, 2018). "Our report documents that loss-of-function mutations in MDH2 are compatible with life and are associated with early-onset severe neurological disease, and the deleterious nature of the identified MDH2 variants has been confirmed by functional assessment in both human cells and a yeast model." (PMID 27989324, 2017).
immune dysfunction (1 paper, 2022). "By integrated genomic and transcriptomic analysis, we reported here that rFSGS patients carried a homozygous c.26C> T mutation in the MDH2 gene in PBMCs with metabolic and immune dysfunction." (PMID 36159820, 2022).
neurodegenerative disease (1 paper, 2025). A disorder of the central nervous system characterized by gradual and progressive loss of neural tissue and neurologic function. "In particular, IDH3G and MDH2 were severely reduced in the brain of PD patients, which was similar to the expression patterns in the brain of patients with other neurodegenerative diseases." (PMID 40730642, 2025).
neuromuscular disease (1 paper, 2020). "The decreasing levels of MDH2 are confirmed in a larger study comprising a total of 493 DMD samples not only in serum but also in plasma (manuscript submitted to Journal of Neuromuscular Diseases)." (PMID 31881125, 2020).
MDH2 also shares sentences with these, for which no sentence is quoted: aspergillosis (2 papers); dementia (2); cervical cancer (1); clear cell renal cell carcinoma (1); COVID-19 (1); esophageal cancer (1); focal segmental glomerulosclerosis (1); gastric cancer (1); gastrointestinal stromal tumor (1); hyperhomocysteinemia (1); hyperlipidemia (1); Hypertension (1); infantile epileptic encephalopathy (1); infectious disease (1); infiltrating ductal carcinoma (1); lobular carcinomas (1); lymph node metastasis (1); mammary adenocarcinoma (1); metastatic tumors (1); Obesity (1); pancreatic insufficiency (1); parasite infection (1); Renal insufficiency (1); Sepsis (1); small cell lung carcinoma (1); spinocerebellar ataxia (1); steatosis (1); tendinopathy (1); triple-negative breast carcinoma (1); tumors of the adrenal (1).
A further 2 diseases each share a sentence with MDH2 in 1 paper.